ITGB8 (integrin subunit beta 8)
Description:
Integrin alpha-V:beta-8 (ITGAV:ITGB8) is a receptor for fibronectin. It recognizes the sequence R-G-D in its ligands. Integrin alpha-V:beta-6 (ITGAV:ITGB6) mediates R-G-D-dependent release of transforming growth factor beta-1 (TGF-beta-1) from regulatory Latency-associated peptide (LAP), thereby playing a key role in TGF-beta-1 activation on the surface of activated regulatory T-cells (Tregs) (Probable). Required during vasculogenesis (By similarity).
Tractability: Small molecule: a structure with a bound ligand is known; a high-quality ligand is known; it belongs to a druggable protein family. Antibody: UniProt places it where antibodies can reach, with high confidence; its Gene Ontology location is reachable by antibodies, with high confidence; UniProt predicts a signal peptide or a membrane-spanning region; the Human Protein Atlas places it where antibodies can reach. PROTAC: ubiquitination databases record sites on it; its protein half-life has been measured.
Gene: Protein-coding gene on chromosome 7 (20,330,609 to 20,415,754, forward strand). Ensembl gene ENSG00000105855.
Subcellular location: Cell membrane
Subcellular location (Human Protein Atlas): Cytosol; Plasma membrane
Pathways (Reactome):
Extracellular matrix organization: Integrin cell surface interactions; Molecules associated with elastic fibres
Signal Transduction: TGF-beta receptor signaling activates SMADs
Gene Ontology:
Molecular function: extracellular matrix protein binding; coreceptor activity; integrin binding
Biological process: cartilage development; cell-matrix adhesion; integrin-mediated signaling pathway; negative regulation of gene expression; positive regulation of angiogenesis; positive regulation of gene expression; vasculogenesis; cell adhesion; cell adhesion mediated by integrin; cell migration; cell-cell adhesion; placenta blood vessel development; anatomical structure morphogenesis; cell differentiation; cell surface receptor signaling pathway
Cellular component: cell surface; extracellular exosome; integrin alphav-beta8 complex; plasma membrane; focal adhesion; integrin complex
Genetic constraint (gnomAD): Loss-of-function variants: 19 observed, 45.43 expected, observed/expected ratio (o/e) 0.42, 90% interval 0.29 to 0.61. The upper end of that interval is the gene's LOEUF score, 0.61, which puts it in group 2 of 6, group 1 being the genes least tolerant of losing a copy. Missense variants: 507 observed, 572.35 expected, observed/expected ratio (o/e) 0.89, 90% interval 0.82 to 0.95. Synonymous variants: 189 observed, 201.05 expected, observed/expected ratio (o/e) 0.94, 90% interval 0.83 to 1.06.
Homologues: Orthologues: chimpanzee ITGB8 (99% identical), macaque ITGB8 (99% identical), pig ITGB8 (92% identical), dog ITGB8 (92% identical), guinea pig ITGB8 (90% identical), rabbit ITGB8 (89% identical), rat Itgb8 (88% identical), mouse Itgb8 (87% identical), tropical clawed frog itgb8 (57% identical), zebrafish itgb8 (37% identical). Paralogues in human: ITGB6 (36% identical), ITGB5 (35% identical), ITGB3 (34% identical), ITGB1 (34% identical), ITGB2 (30% identical), ITGB7 (29% identical), ITGB4 (28% identical), ITGBL1 (14% identical).
Diseases named in the same sentence as ITGB8 in open-access papers:
ITGB8 is named in the same sentence as 66 diseases in open-access papers, as found by Europe PMC text mining. Sharing a sentence is not in itself a finding about the gene and the disease. The quoted sentences say what the papers report.
glioma (26 papers, 2014 to 2025). A benign or malignant brain and spinal cord tumor that arises from glial cells (astrocytes, oligodendrocytes, ependymal cells). "CD133, Nestin and SOX2 expression were positively associated with ITGB8 expression in TCGA and Chinese Glioma Genome Atlas (CGGA) databases, and we further confirmed that ITGB8 was closely correlated with Nestin expression in GBM specimens." (PMID 35676251, 2022). "Furthermore, ITGB8 is associated with radiotherapy in glioma patients and inhibition of ITGB8 leads to radio sensitization of GB cells through postmitotic cell death." (PMID 39417309, 2025). "Our results indicated that ITGB8 expression was elevated in GSCs and positively associated with stem cell markers in glioma tissues, and could be induced by hypoxia and p38 activation." (PMID 35676251, 2022). "hsa_circ_0046701 promotes carcinogenesis by increasing the expression of ITGB8 in glioma, and the expression level of ITGB8 has significantly upregulated in lung cancer tissues compared with normal tissues." (PMID 37651321, 2023). "Another study revealed that circ-TTBK2, also named has_circ_0000594, regulates glioma cell proliferation, invasion, and ferroptosis through the miR-761/ITGB8 axis." (PMID 37332354, 2023). "Our study showed that ITGB8-TGFβ1 affected downstream activation of Smad2/3 and RhoA in glioma cells." (PMID 35676251, 2022). "Circ-TTBK2 uses sponge miR-761 to target ITGB8 to regulate the proliferation, invasion, and ferroptosis of glioma cells, providing a promising biomarker for the clinical treatment of human glioma." (PMID 35688814, 2022). "ITGB8 was detected in multiple cancer types including lung adenocarcinoma, high grade serous ovarian cancer, gastric cancer and glioma, and correlated with poor survival." (PMID 35676251, 2022). "An intracranial glioma model was constructed to assess the effect of ITGB8 on tumor vascularization in vivo." (PMID 35676251, 2022). "Studies have shown an upregulation of circ-TTBK2 in glioma cells and tissues, accompanied by an increase in ITGB8 (integrin subunit beta 8) and downregulation of miR-761." (PMID 35805884, 2022). "We further examined the mRNA expression of ITGB8 in mixed glioma dataset from The Cancer Genome Atlas (TCGA) database." (PMID 35676251, 2022). "Our investigation found that circ_0037655 acted as a tumor-promoting factor in the progression of glioma by regulating the levels of miR-1229-3p and ITGB8, which indicated a different molecular mechanism of glioma." (PMID 34017919, 2021). "miR-1229-3p acted as a tumor inhibitor in the development of glioma through the inhibition of ITGB8 expression." (PMID 34017919, 2021). "Levels of circRNA TTBK2 and integrin subunit β 8 (ITGB8) are upregulated in glioma tissues and cells with downregulated miRNA-761 levels, and circRNA TTBK2 regulates cell proliferation, invasion, and ferroptosis via the miRNA-761/ITGB8 axis." (PMID 33868986, 2021). "The signal networks of circ-TTBK2/miR-761/ITGB8 and circ_0046701/miR-142-3p/ITGB8 have been discovered in glioma reports." (PMID 34017919, 2021). "A research of circ_0046701 indicated its pro-carcinoma action in glioma through enhancing the level of ITGB8 by targeting miR-142-3p." (PMID 34057019, 2021). "Our experiments in vivo also indicated that circ_0037655 expression inhibition suppressed glioma growth via regulating the levels of miR-1229-3p and ITGB8." (PMID 34017919, 2021). "The upregulation of ITGB8 mRNA and protein was found in glioma tissues, as well as the same phenomenon of ITGB8 protein expression in T98G and LN229 cells in contrast with NHA cells." (PMID 34017919, 2021). "In vivo knockdown of circ_0037655 also suppressed glioma tumorigenesis by acting on the miR-1229-3p/ITGB8 axis." (PMID 34017919, 2021). "Taken together, the present study clarified that circ_0037655 sponged miR-1229-3p to promote the expression of ITGB8 to regulate the various cellular behaviors of glioma cells." (PMID 34017919, 2021).
glioma (continued). "Circular RNA TTBK2 modulates ferroptosis, invasion, and proliferation of glioma cells by miR-761/ITGB8 signaling." (PMID 34520391, 2021). "The 3′UTR region of ITGB8 has a binding site for miR-142-3p, and this regulatory relationship has been reported in glioma." (PMID 31615128, 2019). "Overexpression of miR-142 inhibited glioma cell migration and invasion abilities through regulating Rac1 and Integrin Subunit Beta 8 (ITGB8) expression." (PMID 30583549, 2018). "Previous studies have shown that circRNA cZNF292 participates in human glioma tube formation; hsa_circ_0046701 promotes glioma carcinogenesis through the miR-142-3p target ITGB8, and circRNA FBXW7 inhibits glioma tumorigenesis." (PMID 30470262, 2018). "Moreover, the upregulation of circTTBK2-triggered activation of miR-761/ integrin subunit beta 8 (ITGB8) hinders ferroptosis in glioma and facilitates tumor proliferation." (PMID 39309434, 2024). "It has been found that, ITGB8 (β8 integrin) expression was elevated in GBM stem cells and positively associated with stem cell markers in glioma tissues, and could be induced by hypoxia and p38 activation." (PMID 38474320, 2024). "Similarly, circ0046701 and circHIPK3 fostered proliferative and invasive features of glioma cells by targeting the axes miR-142-3p/ITGB8 (integrin subunit beta 8) and miR-654/IGF2BP3 (insulin-like growth factor 2 mRNA-binding protein 3), respectively." (PMID 35269953, 2022). "CircTTBK2 regulates cell proliferation, invasion, and ferroptosis via glioma's miR-761/ITGB8 axis." (PMID 36266731, 2022). "Moreover, it was reported that the circRNA TTBK2 was upregulated in glioma tissues and cells and inhibited ferroptosis via the miR-761/ITGB8 axis to promote glioma proliferation and invasion." (PMID 35342359, 2022). "Furthermore, a significant correlation between ITGB8 mRNA abundance and p38 phosphorylation was observed in TCGA glioma dataset." (PMID 35676251, 2022). "Meanwhile, we found that miR-1229-3p could bind to 3′-UTR of ITGB8 to downregulate the level of ITGB8 in glioma cells." (PMID 34017919, 2021). "The specific circ_0037655/miR-1229-3p/ITGB8 axis was disclosed in glioma research." (PMID 34017919, 2021). "In addition, integrin beta-8 (ITGB8) is a commonly researched regulator in human tumors, including glioma." (PMID 34017919, 2021). "This study showed that downregulation of the expression of circ_0037655 could inhibit glioma progression by acting on the miR-1229-3p/ITGB8 axis." (PMID 34017919, 2021). "miR-1229-3p functioned as a tumor inhibitor in glioma progression by targeting ITGB8." (PMID 34017919, 2021). "Collectively, circ_0037655 could regulate the glioma tumorigenesis in vivo by sponging miR-1229-3p and regulating the expression of ITGB8." (PMID 34017919, 2021). "This circ_0037655/miR-1229-3p/ITGB8 axis is a novel discovery in glioma." (PMID 34017919, 2021). "This study was performed to study whether the regulation of circ_0037655 in glioma was related to miR-1229-3p and ITGB8, intending to provide a better understanding of the functional mechanisms of circ_0037655." (PMID 34017919, 2021). "Moreover, high levels of ITGB8 indicated poor prognosis in glioma dataset." (PMID 35676251, 2022). "Hence, miR-1229-3p/ITGB8 axis partly determined the specific function of circ_0037655 in glioma." (PMID 34017919, 2021). "Thus, ITGB8 downregulation was accountable for the tumor-inhibitory role of miR-1229-3p in glioma." (PMID 34017919, 2021). "The circ_0046701 increases integrin subunit beta 8 (ITGB8) by sequestering miR-143–3p and thereby promoting glioma invasion." (PMID 40453757, 2025). "We first examined ITGB8 expression in five human GSCs (GSC#1-GSC#5) and differentiated glioma cells." (PMID 35676251, 2022). "In glioma, the circular RNA Tau tubulin kinase 2 (Circ-TTBK2) promotes cell proliferation and invasion while inhibiting ferroptosis by sponging miR-761 and activating Integrin Subunit Beta 8 (ITGB8)." (PMID 39595619, 2024).
glioma (continued). "Besides, TTBK upregulates the level of integrin subunit beta 8 (ITGB8) and affects the proliferation, invasion, and promotes ferroptosis in glioma cells." (PMID 36349142, 2022). "Further study found that circ-TTBK2 was a sponge of miR-761 to modulate ITGB8, and knockdown of circ-TTBK2 induced lipid ROS production, which promoted ferroptosis and retarded cell proliferation, invasion in glioma cells, suggesting a potential biomarker for clinical glioma treatment." (PMID 35006436, 2020). "Our data showed that ITGB8 in GSCs, but not differentiated glioma cells, could be induced by hypoxia." (PMID 35676251, 2022). "In addition to these well-established glioma markers, we identified several other proteins that have never been associated with glioma biology including (e.g., SLC1A3, CLU, LGALS3BP, ANGPTL2, CRYAB and ITGB8)." (PMID 25360666, 2014).
lung carcinoma (14 papers, 2015 to 2026). "In lung cancer models, high expression of ITGB8 in cancer cells can induce cancer-associated fibroblasts (CAFs) to contract collagen, polarize macrophages to the M2 phenotype, and upregulate ITGB8 in tumor cells, thus forming a positive feedback loop." (PMID 41602481, 2026). "ITGB8 was also found to be amplified in the EGFR-mutated group of lung cancer." (PMID 32175330, 2020). "ITGB8 has been shown to confer paclitaxel and cisplatin resistance in OC and paclitaxel resistance in lung cancer." (PMID 38814534, 2024). "In lung cancer, circDNER enhances paclitaxel resistance and tumorigenicity of lung cancer via targeting miR-139-5p/ITGB8." (PMID 36980210, 2023). "Further experimental studies showed that ITGB8 silencing inhibits the invasion and migration of lung cancer cells and arrest the cell cycle at G0/G1." (PMID 33335550, 2020). "ITGB8 has been reported to be overexpressed in various cancers, especially in lung cancer and lung AD cell lines and has recently been found to be related to gefitinib and cisplatin resistance in cancer." (PMID 32175330, 2020). "The transcription levels of ITGA11, ITGB4 and ITGB8 between lung cancer and normal samples in ONCOMINE database." (PMID 31875161, 2019). "Using ONCOMINE database, we investigated the transcription levels of ITGA11, ITGB4 and ITGB8 in lung cancer vs. normal samples." (PMID 31875161, 2019). "Changes in E-cadherin and Snail expression have been reported in lung cancer cells where ITGB8 was silenced." (PMID 25886373, 2015). "Furthermore, we analyzed ITGA11, ITGB4 and ITGB8 mRNA expression level in both lung cancer and normal tissues using the TCGA-LUAD and TCGA-LUSC original data." (PMID 31875161, 2019). "Moreover, It has been reported that ITGB8 silencing could suppress the metastatic potential of human lung cancer cell lines A549 and PC." (PMID 31875161, 2019). "Among the many predicted targets, seven genes (SOX4, ZEB2, AVL9, PTPN9, RAB22A, ITGB8 and SIX1) that have been reported to play an oncogenic role in lung cancer were further analyzed." (PMID 35287543, 2022). "Similar to the present data, a meta-analysis in lung adenocarcinoma patients also exhibited a strong relationship between ITGB8 and COMP, contributing to the regulation of lung cancer metastasis and poor treatment outcomes." (PMID 35056061, 2021). "Likewise, circR-DNER sponges miR-139-5p to upregulate Integrin subunit beta 8 (ITGB8) expression, which contributes to lung cancer progression and PTX resistance." (PMID 40296912, 2025).
ovarian carcinoma (11 papers, 2019 to 2025). A malignant neoplasm originating from the surface ovarian epithelium. "This may partly explain the association between reduced OS and ITGB8 overexpression in ovarian cancer patients." (PMID 32565741, 2020). "In ovarian cancer, ITGB8 had been demonstrated to be associated with drug resistance." (PMID 32565741, 2020). "The mRNA levels of ITGA1, ITGB1, ITGB3, and ITGB8 were found to be highly elevated in ovarian cancer tissues compared to those in normal ovarian tissues." (PMID 37596406, 2023). "LncRNA TCF7 has been found to enhance cell viability, migration, invasion via modulation of ITGB8 in epithelial ovarian cancer." (PMID 36105363, 2022). "Molecular experimental data showed that lncRNA TCF7 promoted the expression of ITGB8 and exerted its oncogenic function in ovarian cancer." (PMID 36105363, 2022). "ITGB8 is significantly upregulated in ovarian cancer tissues, and the OS and disease-free survival of patients with ovarian cancer with high ITGB8 expression are significantly shortened." (PMID 33335550, 2020). "MiR-199a-3p increases the cisplatin sensitivity of ovarian cancer cells by downregulating ITGB8 (Integrin subunit Beta 8) expression." (PMID 31754335, 2019). "Moreover, the overexpression of miR-199a-3p enhances the cisplatin sensitivity of ovarian cancer cells through downregulating ITGB8 expression, leading to cell cycle arrest and increased cell apoptosis." (PMID 40732337, 2025). "Furthermore, ITGB8 was significantly upregulated in ovarian cancer tissues compared with that in normal ovary tissues." (PMID 31875161, 2019). "Abnormal expression of the miR-199 cluster, for example, has been confirmed to increase the sensitivity of ovarian cancer cells to DDP through silencing the expression of protein tyrosine phosphatase non-receptor type 3 (PTPN3), integrin subunit beta 8 (ITGB8) and discoidin domain receptor 1 (DDR1)." (PMID 34512721, 2021).
glioblastoma (9 papers, 2014 to 2025). The most malignant astrocytic tumor (WHO grade IV). "Consistently, ITGB8 was also upregulated in glioblastoma tissues and its upregulation was associated with worse clinical outcome." (PMID 32565741, 2020). "ITGB8 (encodes integrin-β8) promotes tumor angiogenesis and invasiveness in glioblastoma, functions necessary for normal first trimester development when placental cells invade maternal tissue and access maternal blood." (PMID 29335024, 2018). "Furthermore, high expression levels of ITGB8 have already been associated with angiogenesis in other tumor types, such as glioblastoma." (PMID 35887120, 2022). "ITGB8 has also been found to enrich glioblastoma stem cells (GSCs), with co-expression of ITGB8 and the stemness marker SOX2 observed in ITGB8 (+) glioblastoma cells." (PMID 39239559, 2024). "In glioblastomas, miR-93 promoted the growth, migration and tube formation of endothelial cells by inhibiting the expression of ITGB8, which is a primary receptor of extracellular matrix proteins and regulates the adhesion between cells and the ECM." (PMID 25578493, 2015). "Furthermore, ITGB8 is an essential regulator of angiogenesis and tumor invasiveness in glioblastoma." (PMID 25277193, 2014).